VIM (vimentin)
Diseases named in the same sentence as VIM in open-access papers (continued):
Sharing a sentence is not in itself a finding about the gene and the disease.
cancer (continued). "Specifically, levels of the pVHL and RhoA were decreased, and the expression of HDAC1, CD44 (a cancer stem cell [CSC] marker), Snail, and vimentin (EMT markers) in normal hRECs and various renal tumor cell types (Caki-2, ACHN, and 798-o) was upregulated." (PMID 30872677, 2019). "Among 348 altered genes, Vimentin and Tgf-β2 were significantly reduced, as well as genes involved in TGF-β signaling pathways which are the main mediators of cancer EMT." (PMID 31808751, 2019). "We observed increased expression of mesenchymal markers, such as β-catenin, α-SMA, and vimentin, when the cancer cells were co-cultured with Tregs, indicating that Tregs promote EMT-related events in cancer cells." (PMID 31690033, 2019). "TGF-β, a key driver of EMT, induces the expression of vimentin and N-cadherin and represses E-cadherin expression, thus promoting EMT and cancer metastasis." (PMID 30823890, 2019). "Of the top down-regulated genes, PLAGL1, CTH and VIM are positively correlated with HNSCC, while increased expression of RMRP, SULT1 and LTBP1 has been recorded in other cancers." (PMID 31827722, 2019). "Epithelial-mesenchymal transition (EMT), characterized by decreased E-cadherin expression and increased vimentin expression, mediates cancer cell invasion and metastasis, and transforming growth factor-β1 (TGFβ1) can independently induce EMT in cancer cells." (PMID 30992007, 2019). "Vimentin, a 57kDa protein of the type III IF family and a canonical marker of EMT, has been demonstrated to be involved in VM in a variety of cancers." (PMID 31428643, 2019). "Vimentin, a canonical marker and actor of EMT, has accordingly been extensively described as a prognostic marker in various cancers." (PMID 31546725, 2019). "Because the invasion and metastasis of cancers are related to epithelial‐mesenchymal transition (EMT), we carried out staining for N‐cadherin, vimentin, and E‐cadherin to examine the relationship between EMT and RGS5." (PMID 31049219, 2019). "Most notably, in cancer, vimentin is most frequently used as a marker of mesenchymal cell types in epithelial-to-mesenchymal transition (EMT), a process that is critical to cancer metastasis." (PMID 31126068, 2019). "Cancer cells undergoing the EMT process exhibit upregulated expression of N-cadherin, vimentin, fibronectin, and snail and downregulated expression of E-cadherin." (PMID 31252615, 2019). "The expression of vimentin, Snail, and ZEB1 in cancer cells co-cultured with T-HESCs was examined by qPCR." (PMID 31040369, 2019). "We calculated and plotted the Pearson correlation coefficient r, between the expression of TF genes and the expression of CDH1 or VIM, across 1038 CCLE microarrays for cancer cell lines representing various degrees of E and M states." (PMID 31019211, 2019). "Previous studies have shown that vimentin regulated Ras, Slug and TGF glows in cancer cells, which is necessary for EMT induction." (PMID 30881302, 2019). "Immunohistochemical analysis of vimentin and CD44 confirmed the evidence that in the presence of microcalcifications, both benign and malignant breast lesions are characterized by numerous breast cells with a mesenchymal phenotype." (PMID 31718020, 2019). "Whereas Wi-A binds to vimentin and heterogeneous nuclear ribonucleoprotein K (hnRNP-K) with high efficacy and downregulates its effector proteins, MMPs and VEGF, involved in cancer cell metastasis, 3βmWi-A was ineffective." (PMID 31757995, 2019). "Cancer cells isolated by the sphere formation assay displayed self‐renewal properties, upregulation of EMT markers (vimentin, Snail/Slug and N‐cadherin), stemness and developmental genes (CD105, CD133, CXCR4, NANOG, MYCN, and WNT)." (PMID 30883740, 2019). "A mesenchymal signature (VIM, FN1, LOX, GPC6, ZEB1) was defined as the highest co-correlated mesenchymal marker set in Cancer Cell Line Encyclopedia (CCLE) NSCLC cell lines." (PMID 31581742, 2019).
cancer (continued). "We have summarized the impact of HDIs on epithelial (E-cadherin, β-catenin) and mesenchymal (N-cadherin, vimentin) markers, EMT activators (TWIST, SNAIL, SLUG, SMAD, ZEB), as well as morphology, migration and invasion potential of cancer cells." (PMID 30691229, 2019). "In addition, epithelial-mesenchymal transition (EMT)-related proteins, including β-catenin, E-cadherin, N-cadherin, snail, vimentin, and ZO-1, by which cause the loss of cell–cell junction and dissemination of cancer cells, were not regulated by ISLA treatment." (PMID 30618749, 2018). "One such protein is vimentin, which is classified as a type III intermediate filament (IF) protein abundant in motile mesenchymal cells, various types of tumors, and cancer cell lines." (PMID 29724197, 2018). "One of the main characteristics of cancer cells undergoing EMT is the enhanced expression of mesenchymal markers, such as vimentin." (PMID 30181714, 2018). "5-FU also inhibited cancer cell migration and invasion by downregulating the expression of MMP-9, mesenchymal marker vimentin and EMT-inducing transcription factor snail and simultaneously upregulating the expression of epithelial marker E-cadherin." (PMID 29587668, 2018). "At the same time, cancer cells exhibited four different signals from staining with anti-cytokeratin Brilliant Violet 421, anti-ALDH1 AlexaFluor 488, anti-vimentin Alexa Fluor 594, and DRAQ5 nuclear dye." (PMID 31164563, 2018). "Studies have revealed that HIF-1α can promote cancer cell metastasis through EMT by upregulating snail, twist, and vimentin expression." (PMID 29661250, 2018). "It represses E-cadherin expression and induces the expression of vimentin and N-cadherin, thus promoting EMT and cancer metastasis." (PMID 29510731, 2018). "In our study, the down-regulations of MMP-2, MMP-9, and Vimentin reflected the inhibitory effects of APS on migration and invasion of MG63 cells, suggesting that APS exerted anti-cancer role in OS also by inhibiting cell migration and invasion." (PMID 30462772, 2018). "In cancer tissues, the expression of E-Cadherin was negatively correlated with MLL2 expression while Vimentin expression was positively correlated with MLL2 expression." (PMID 29532228, 2018). "They used four established EMT markers—CDH1 (epithelial marker, E type), CDH2 (mesenchymal marker, M type), VIM (M type), and FN1 (M type)—as seeds to develop a pan-cancer EMT signature on the basis of TCGA pan-cancer RNA-Seq data." (PMID 29426364, 2018). "Direct phosphorylation of vimentin by AKT1, a known cancer promoting kinase, protects it from caspase mediated cleavage and blocks apoptotic progression." (PMID 29925392, 2018). "More recently, transcriptomic data from TCGA and Cancer Cell Line Encyclopedia (CCLE) have been used to define a pan-cancer EMT signature based on the expression of E-cadherin and Vimentin alone." (PMID 29293502, 2018). "VIM assembles into focal adhesions and it is required for FAK activity and localisation at the cellular leading edge of motile cancer cells." (PMID 29844309, 2018). "In the process of cancer metastasis, MMP-9, CD44v6 and vimentin are responsible for cell migration, invasion and cell-matrix adhesion." (PMID 28774312, 2017). "In particular, with enhanced PSC-derived Galectin-1 expression, Vimentin and MMP9 expression increased in the cytoplasm of the stromal area around the PDAC cells and E-cadherin expression decreased on the cancer cell membrane." (PMID 29156810, 2017). "Several studies have defined the targets of miR-138 such as VIM, RhoC, Hif-1α, CCND1 and Sirt1 in cancer types other than RCC, which are often involved in cell migration, EMT, DNA damage repair, senescence." (PMID 28978010, 2017). "Some of these markers such as Vimentin and MMP2&9 are accurate indicators for the invasive nature of the found cancer cells." (PMID 29259164, 2017).
cancer (continued). "Conversely, increased N-cadherin, vimentin, fibronectin, Zeb1, Twist, and Snail expression and down-regulation of E-cadherin were detected in CLCA4 silenced cancer cells." (PMID 29190973, 2017). "Previous studies have reported that miR-200c inhibits EMT processes in cancer cells by regulating the expression of EMT markers including E-cadherin, N-cadherin, TCF8/ZEB1, Snail, vimentin, and β-catenin." (PMID 28727734, 2017). "This is also accompanied by increased expression of CXCL12, CXCL10, as well as markers of cancer progression, including CD44, ZEB1 and vimentin." (PMID 28445977, 2017). "Infact, protein lysates from harvested resistant tumors showed higher vimentin levels and EGFR-inhibitors resistant cancer cells established in vitro showed high invasive and migrative abilities." (PMID 28416737, 2017). "N-cadherin, like Vimentin, is a mesenchymal marker, and the increase of N-cadherin and decrease of membrane E-cadherin is a common molecular event during EMT in cancer." (PMID 28198387, 2017). "Correspondingly, the epithelial phenotype with high CDH1 expression, low expression of VIM and low expression of EMT-inducing transcription factors correlates with high expression of cancer stem cell markers CD133 and EPCAM." (PMID 29299154, 2017). "We screened for cancer cells expressing at least one EMT marker, such as ACTA2, EPCAM, CD44, THY1, VIM, FN1, ZEB1 or CDH1." (PMID 29079795, 2017). "To investigate the mechanism by which these miRNAs induced an MET phenotype, we evaluated the EMT marker genes E-cadherin, Vimentin, ZO-1, ZEB1 and Snail in several cancer cell lines, Panc1, KP4-4, SU.86.86, BxPC3 and MDA-MB-231." (PMID 28638102, 2017). "Recently, many epigenetic biomarkers have been studied in cancer diagnosis, including hMLH1, E-cadherin, CDKN2A, CDKN2B and APC in GC and SEPT9, SFRP2, THBD, SDC2, VIM and FBN1 in CRC." (PMID 29137404, 2017). "Loss of adherens junction proteins, typically E-cadherin, and upregulation of mesenchymal markers such as fibronectin, vimentin, and N-cadherin are major molecular events that dr ive EMT in various cancer cells." (PMID 29348886, 2017). "In cancer cells, previous studies have shown that EGCG binds to Fas and induces Fas‐mediated apoptosis 27 and that it inhibits the phosphorylation of vimentin, an intermediate filament, to suppress cell proliferation." (PMID 29226083, 2017). "We examined the expression levels of vimentin and USP14 in our GC sample cohorts by RT-qPCR and found higher expression levels in cancer compared with the paired adjacent normal tissues." (PMID 27448976, 2017). "To explore the mechanism of NLS on anti-metastasis, we detected the expression of β-catenin, E-cadherin, Vimentin and Snail in PC3 and DU145 cells, which are known factors involved in epithelial-mesenchymal transition (EMT) and cancer metastasis." (PMID 28134352, 2017). "For example, the CMS4 marker VIM is expressed in fibroblasts, but have higher expression among CMS4 cancer cells than CM2–3 and is therefore a useful template gene." (PMID 29192179, 2017). "Protein levels of cancer stem-like biomarkers (CD133, ALDH1, Lgr5, Vimentin, Snail1), and the proliferative rate of 131I-AC133.1 mAb group were lower than other groups (P<0.001); while its protein level of E-cadherin was higher than other groups." (PMID 28430648, 2017). "Vimentin is a component of intermediate filaments whose expression facilitates the reconstruction of the cancer cell cytoskeleton during EMT and endows the cancer cell with a spindle-like shape suitable for migration." (PMID 29113414, 2017). "TGF-beta treatment significantly increased the expression of vimentin and PGC-1alpha, and decreased E-cadherin levels in SKOV-3 cancer stem cells." (PMID 29340100, 2017).
cancer (continued). "All three cell lines express EGFR and TLR4 receptors, although at different levels; notably, MCF-7R has lost E-cadherin expression and acquired Vimentin, while showing higher levels of EGFR and alpha-enolase, all features of cancer cell aggressive phenotype." (PMID 28630480, 2017). "The carcinoma component of the tumors showed differentient labeling for CAIX, CD10, vimentin, CK7 and CD117 in CCRCC vs ChRCC, but the sarcomatoid component lost the specificity for these markers (p < 0.05)." (PMID 28449664, 2017). "On the whole, the expressions of vimentin, EMA, SMA, and Bcl-2 were significantly different between carcinoma and sarcomatoid cells (P < 0.05)." (PMID 28449664, 2017). "The expressions of CAIX, CD10, vimentin, CK7 and CD117 in the carcinoma component between CCRCC and ChRCC showed significant differences (P < 0.05)." (PMID 28449664, 2017). "Vimentin is reported as an important mesenchymal marker, and plays a central role in EMT in malignant tumours including cellular adhesion and migration, cytoplasmic microtubule assembly and cytoskeleton remodelling." (PMID 27412958, 2016). "The switch of E-cadherin to N-cadherin and increase of EMT proteins including vimentin, slug, and snail have been shown to be important hallmarks of EMT in cancer cells." (PMID 27330411, 2016). "Since EMT has been associated with the acquisition of migration and invasion of cancer cells, we detected the expression of EMT marker, E-cadherin and vimentin after tigecycline treatment." (PMID 26621850, 2016). "Therefore, vimentin might be a relevant target for cancer therapeutic interventions." (PMID 27072512, 2016). "In cancer cells, EMT is usually characterized by the suppression of epithelial markers, such as E-cadherin, and expression of mesenchymal markers, such as vimentin and N-cadherin through a complex transcriptional reprogramming." (PMID 27119231, 2016). "When cancer cells were transferred back to normoxia, higher expression of SCEL and E-cadherin and lower expression of vimentin and Lgr5 were restored." (PMID 27013588, 2016). "EMT is essential for cancer cell invasion and metastasis; several biomarkers involved in EMT have been identified, including E-cadherin, N-cadherin, fibronectin, and vimentin." (PMID 27271583, 2016). "Despite that, VIM and PENK were excluded from the following analysis because only very few cancer patients had VIM or PENK hypermethylation." (PMID 27891190, 2016). "Accordingly, cancer stem cell-like markers and epithelial-mesenchymal transition (EMT) biomarkers (vimentin up-regulation and E-cadherin and β-catenin down-regulation) are associated with recurrence of OSCC patients." (PMID 27835882, 2016). "Both HGF and fibroblasts induced the expression of vimentin in DU145 cells, confirming that they promote EMT in cancer cells." (PMID 27121052, 2016). "We showed that second-line treatment with everolimus may affect mesenchymal cancer cell differentiation and angiogenesis recovery following acquisition of sunitinib resistance; tumors of mice treated with everolimus also had decreased vimentin and increased E-cadherin expression." (PMID 27509260, 2016). "We first analyzed ovarian (SKOV3 and NIH:OVCAR3), colon (HT29), and lung (H1299) cancer cell lines for the expression of TTP, the epithelial marker E-cadherin, and the mesenchymal markers N-cadherin and vimentin by RT-PCR and Western blot." (PMID 26840564, 2016). "However, how vimentin contributes to EMT-related cancer malignancy is still unknown." (PMID 27966589, 2016). "EMT is a prerequisite for cancer cells to become highly metastatic, and EMT occurs as the result of increased expression of EMT-related proteins, such as N-cadherin, Snail, and vimentin." (PMID 26716415, 2016). "As expected, in cancer cells, NKX6.3 expression regulated the expression of EMT-related proteins, such as E-cadherin, Zo-1, N-cadherin, β-catenin, Snail, Slug, Vimentin and ZEB-1." (PMID 27333045, 2016).
cancer (continued). "Gene expression levels of VIM and CD44 in MDA-MB-231 cancer cells were dramatically suppressed when the cells were grown in MEM in comparison to cells grown in DMEM." (PMID 25776572, 2015). "Our results demonstrate that PPIX treatment inhibited the expression of vimentin, Zeb1/2, snail, slug, and twist, EMT markers upregulated in mesenchymal HCC cells, supportive of its anti-cancer potential against HCC with EMT phenotype." (PMID 25714015, 2015). "However, how vimentin contributes to EMT-related cancer malignancy is unknown." (PMID 25965826, 2015). "Vimentin is one type of EMT protein marker, which is present in mesenchymal cells and involved in cancer progression." (PMID 25965826, 2015). "Vimentin also regulates the expression of the EMT-related transcription factor, slug, to further enhance EMT phenotypes and cancer malignancy." (PMID 25965826, 2015). "There was a significant downregulation of mRNA levels of mortalin and several other proteins, including MMPs, vimentin, β-catenin, TGF-β and Wnt-3a, involved in cancer cell metastasis in embelin-treated cells as compared to their control counterparts." (PMID 26376435, 2015). "The mRNA levels of cancer stem-related genes (CD133, CD44), EMT-related markers (N-cadherin, vimentin and E-cadherin) and transcriptional factors (Snail, Slug and Twist) were detected under different experimental conditions." (PMID 26452130, 2015). "With the increase in vimentin, slug expression was increased, and EMT-related gene expression was further elevated to further promote cancer malignancy." (PMID 25965826, 2015). "Classical markers of EMT, Twist, and vimentin, have been identified in breast cancer patients and specifically show elevated expression in patients with metastatic cancer relative to patients with early-stage cancer, supporting the hypothesis that EMT controls the metastatic potential of CTCs." (PMID 25852822, 2015). "The possible association of vimentin with the clinically aggressive behavior of tumors described by others may be explained by the correlation of vimentin expression with a lack of steroid receptors and poor differentiation of cancer." (PMID 24527079, 2014). "As shown, these miRNAs are active regulators of the expression of several cancer-related mRNAs, including ZEB1, ZEB2, VIM, VEGFA, NTRK3 and SPDEF, and most of the miRNAs are cancer-related." (PMID 24512620, 2014). "In agreement with cancer stem cell markers, the expression levels of EMT markers, vimentin and slug, were clearly decreased upon Stattic treatment." (PMID 24297508, 2014). "Cancer specificity and sensitivity of CDO1 methyaltion was proven to be equal to those of either SEPT9 or Vimentin methylation in CRC, where the AUC of the ROC curve to differentiate cancer tissues from the corresponding normal mucosa was 0.96." (PMID 25469504, 2014). "We performed a correlation analysis between TGF-β and α-SMA, TGF-β and vimentin, TGF-β and E-cadherin, Twist and α-SMA, Twist and E-cadherin and Twist and α-SMA in all the cancer samples." (PMID 25189096, 2014). "Vimentin expression as another indicator for EMT induction in ductal epithelial cells was already detectable in 47% of CP tissues and similarly expressed in carcinoma cells in PDAC tissues." (PMID 24797069, 2014). "In our study, Consistent with the reduced metastatic behavior of these cancer cells, the epithelial marker E-cadherin increased in BMI1 siRNA group cells, whereas the mesenchymal marker vimentin and twist decreased." (PMID 23820733, 2013). "Western blot analysis to assess SIRT1, Vimentin, E-Cadherin, LKB1, and β-actin expression was performed in gastic cancer cell lines." (PMID 23768087, 2013). "Cancer cells engaging EMT process express mesenchymal genes, such as Vimentin, snail, and slug, while the expressions of epithelial marker genes, such as E-cadherin and ZO-1 are decreased." (PMID 23418515, 2013).